PRL (prolactin)
Diseases named in the same sentence as PRL in open-access papers (continued):
Sharing a sentence is not in itself a finding about the gene and the disease.
tumor (continued). "He had a partial transsphenoidal resection of the tumor and on histopathology the immunostaining was positive for GH and prolactin." (PMID 35456261, 2022). "These encouraging results led to the determination of criteria for discontinuation of treatment, which are summarized as normal prolactin under a low dose of cabergoline (0.5 mg/week) and disappearance or 50% decrease in tumor size on MRI." (PMID 36540468, 2022). "There was also a significant relationship between preoperative tumor size and postoperative prolactin level (OR: 5.29 (1.65, 8.92), p = 0.006)." (PMID 35365091, 2022). "Imaging has shown significant reduction in tumour volume from an estimated 28 ml at diagnosis to 1 ml in 2019; latest prolactin level is 5892 mU/l, and he has a minor ongoing visual field impairment." (PMID 33010004, 2021). "In some MEN1 patients, poorly differentiated PIT1-lineage tumours, previously known as “silent subtype 3 adenoma”, have been observed, with a variable combination of GH, prolactin, α-subunit and thyroid-stimulating hormone." (PMID 33805450, 2021). "Since increased circulating levels of prolactin have been associated with mammary tumorigenesis, it suggests a correlation between the significant cumin-mediated reduction observed in the prolactin level and tumor inhibition." (PMID 34201250, 2021). "For example, the infiltration of CD8+T cells was positively correlated with PRL and PRL and GH immunostaining in the tumor and was also positively correlated with the invasions of PAs." (PMID 34090476, 2021). "Noteworthy, all these studies have been performed in patients well responders to long-term treatment with DA at conventional doses, namely patients who achieved PRL normalization and a concomitant reduction of at least 50% in tumor volume." (PMID 34917030, 2021). "Elevated serum prolactin levels and increased expression of the long form prolactin receptor (LFPRLR) on tumor parenchyma are associated with higher risks of cancer progression." (PMID 34375938, 2021). "A lower PRL level before GK (a sign of less tumor invasiveness of regional structures such as the cavernous sinus) is associated with better hormonal remission in several studies." (PMID 34638482, 2021). "The consequences in the pituitary include overproduction of GH and sometimes also prolactin and hyperplasia or tumour." (PMID 33805450, 2021). "To overcome this issue, we generated BCC clones that release PRL under the control of doxycycline, and found that SMI-6 induced rapid and dramatic suppression of PRL-induced tumor growth in athymic mice inoculated with such clones." (PMID 34071395, 2021). "In vivo, prolactin has the capacity to affect function of the tumor parenchyma both directly and indirectly via the Tregs." (PMID 34375938, 2021). "In contrast, with a patient presenting with a PRL of > 204 μg/L (> 4338 mU/L) it is highly probable that the tumour will be a macroadenoma as this study highlights." (PMID 33963239, 2021). "Some investigators have challenged the concept of the tumor-promoting actions of PRL, arguing that elevated PRL and/or high expression of the PRLR can actually serve as markers of favorable clinic-pathological parameters and better patient survival." (PMID 34071395, 2021). "Baseline serum PRL concentrations were strongly correlated to tumour dimension (r = 0.750, p = 0.001)." (PMID 33963239, 2021). "Prolactin levels often correlate with tumor size, so those greater than 500 μg/L likely indicate the presence of a prolactin-secreting macroadenoma." (PMID 33946142, 2021). "While both residues are phosphorylated in tumor grades I-III, pS726 increases with tumor grade, and is PRL-responsive." (PMID 34188118, 2021). "Bromocriptine and cabergoline are the first choices to treat prolactinoma, as they can rapidly shrink tumour size, improve compression and reduce the PRL level." (PMID 34814904, 2021).
tumor (continued). "We also found increased tumor growth and development of metastases in mice implanted with PRL-overexpressing BC xenografts." (PMID 34071395, 2021). "A 12-months combined treatment with octreotide long-acting release (LAR, 30 mg monthly), achieved a nadir in PRL level (100 μg/L) and a partial response in tumor size (30 × 18x12mm)." (PMID 34173929, 2021). "Constitutive PRL signaling in mammary glands affects the tumor environment by altering the RAS pathway activation and induces aggressive tumors." (PMID 34572912, 2021). "Proliferative metastatic cells secrete prostaglandin PGE2 that activates prolactin secretion in nearby fibroblasts, which facilitates tumor cell proliferation." (PMID 35008251, 2021). "The Endocrine Society's Clinical Practice Guidelines recommend DAs as first-line therapy to lower the PRL level, decrease tumour size, and restore gonadal function for most patients with prolactinoma." (PMID 34504526, 2021). "In this study, we investigated a protein kinase-PDZ Binding Kinase (PBK)/T-LAK Cell-Originated Protein Kinase (TOPK) as a candidate protein regulating prolactin (PRL) secretion and tumor growth of prolactinomas." (PMID 35126305, 2021). "PRL enhances oestrogen sensitivity, promotes tumour differentiation and reduces therapeutic sensitivity through this mechanism." (PMID 34651424, 2021). "Giant prolactinomas are defined as adenomas with tumor diameters ≥ 4 cm and prolactin levels (PRLs) ≥ 1000 ng/mL, accounting for only 0.5% of all pituitary adenomas and are predominantly found in men." (PMID 34771538, 2021). "A case series with DAs and metformin over 8-14 months have noted both PRL normalization and significant tumor reduction." (PMID 33841328, 2021). "Workup revealed an elevated prolactin level, and imaging demonstrated erosion of the anterior sellar floor and soft tissue within the sphenoid sinus, concerning for tumor." (PMID 33728130, 2021). "Recently, we and others showed that prolactin promotes tumor metastasis in vivo; in our study, we more specifically showed it was prolactin working through the long rather than short forms of the PRLR." (PMID 34375938, 2021). "DAs are effective in normalizing prolactin levels (68% of patients), reducing tumor size (62% of patients) and relieving infertility (53%) and other symptoms." (PMID 34774043, 2021). "There was also a weak positive relationship between PRL-R expression in breast tissues (tumor and adjacent tissue) and serum PRL levels." (PMID 34945164, 2021). "In the mice with subcutaneous xenograft tumors, continuous injection of prolactin into the tumors for 10 days significantly decreased the tumor weights." (PMID 33664869, 2021). "Here we report a patient with prolactinoma who was resistant to high-dose cabergoline (CAB) treatment, demonstrating a continuous increase in both the tumor volume and the prolactin (PRL) level." (PMID 33776913, 2021). "DAs are highly effective in normalising the PRL level and reducing tumour size and are recommended as the first choice for essentially all patients with prolactinomas." (PMID 34504526, 2021). "Tumors derived from shNEK2-transfected prolactin tumor cells also weighed significantly less than those from the control group (0.204±0.071 vs 0.437±0.061g; P < 0.01)." (PMID 33754007, 2021). "Several definitions have been proposed to describe DAs resistance, one of the widely accepted is a failure to normalize PRL levels and to reduce tumor volume (at least 50%) with 2 mg/week of CAB." (PMID 34173929, 2021). "Mammosomatotroph tumors are composed of strongly acidophilic, densely granulated cells that express PIT1 but also the estrogen receptor alpha (ERα) and they have strong cytoplasmic GH reactivity and αSU with variable amounts of prolactin in most tumor cells." (PMID 34067494, 2021).
tumor (continued). "In our series we did not observe a complete resistance to CAB; nevertheless, in all cases, the highest tolerated doses of CAB (ranging from 3 to 5 mg/week) were able to achieve only a sub-normalization of PRL levels and a mild reduction of tumor burden." (PMID 34173929, 2021). "For the past three decades, we and others have endeavored to establish that PRL aggravates BC by accelerating tumor growth, invasion, and metastasis, as well as by increasing chemoresistance." (PMID 34071395, 2021). "The animals in the tumor time point receiving E2 treatment showed a dramatic increase in the plasma prolactin level (4629 ± 839), which was very significantly mitigated with dietary cumin (1767 ± 405 ng/mL; p < 0.001) at 26 weeks." (PMID 34201250, 2021). "Addition of an aromatase inhibitor (ANA) to the dopamine agonist therapy improved the control of prolactin levels and induced tumour regression." (PMID 34173929, 2021). "We associated ANA to a reduced dose of CAB (3.5 mg/week): the patient achieved a PRL leverel reduction (145 μg/L) in 3 months, with a nadir of 50 μg/L, and a consistent shrinkage in tumor volume." (PMID 34173929, 2021). "Eight months after the second GKS treatment, MRI in July 2014 indicated that the tumor size was reduced slightly, and the serum prolactin levels decreased to 126.0 ng/mL." (PMID 34715828, 2021). "Consistent with the faster tumor-growth rate and development of larger tumors in mice inoculated with vehicle-transfected cells, plasma PRL and serum GH levels were also reduced by 38% and 22%, respectively, in the shNEK2-transfected group." (PMID 33754007, 2021). "Prolactinoma cells express DA receptors, and DA(s) can effectively inhibit prolactin secretion and shrink tumours by binding to DA receptors on the surface of most patients’ cells." (PMID 34814904, 2021). "In the in vivo experiment, HI-TOPK-032 (10 mg/kg) inhibited the tumor growth and PRL expression & secretion in prolactinoma model rats." (PMID 35126305, 2021). "These tumor cells were positive for Pit‐1, PRL and Syn, with perinuclear punctated structures immunopositive for cytokeratin 18 (CK18)." (PMID 34286902, 2021). "Prolactinomas directly secrete prolactin, which can be measured in the serum and used in conjunction with tumor volume to diagnose a prolactinoma with high predictive value." (PMID 34956896, 2021). "Knockout of MAPK14 significantly inhibited tumor overgrowth, and PRL expression was decreased in estradiol-induced mice." (PMID 32894113, 2020). "Using tumor cell death as the measure, we report a more than additive effect from co-treatment with well-tolerated doses of calcitriol together with S179D PRL." (PMID 33179012, 2020). "It must be emphasized that the present study aims to look at the impact of DA both in terms of tumour size as well as prolactin level to define responsiveness." (PMID 32429916, 2020). "Patient 16 discontinued DA after 5 months of treatment but showed an increase in serum PRL level and tumor size after 3 months, and received TSA due to premature withdrawal failure, and personal preference." (PMID 32849307, 2020). "The 4 most powerful predictors are: sex, tumour volume, the moment of prolactin normalization and the presence of a cystic, hemorrhagic or necrotic component (before the start of the dopamine agonist treatment)." (PMID 32429916, 2020). "The majority of patients with prolactinoma respond to dopamine agonist bromocriptine, and treatment results in the reduction of tumor size and decreased PRL production and secretion." (PMID 32894113, 2020). "Dopamine agonists (bromocriptine, BCT) are the first choice for PRL-PA treatment (not applicable to patients with rapid visual loss and visual field defects), followed by surgery, which can reduce tumor size and prolactin levels." (PMID 33472173, 2020). "When resistance (failure to achieve PRL normalization and/or a tumour size reduction of ≥50%) is established to a particular patient, there are different therapeutic options." (PMID 32429916, 2020).
tumor (continued). "Dopamine receptor type 2 (DRD2) represents the principle target for pharmacological therapy with dopamine agonists (DAs) due to its ability to induce tumor mass shrinkage and to regulate excessive hormone secretion in prolactin (PRL)-secreting PitNETs." (PMID 33664708, 2020). "Secondary (or acquired) resistance to DAs is very rare and describes patients that initially responded to DA but later showed increasing prolactin levels and/or tumor enlargement." (PMID 31522358, 2020). "Patients with mutant SF3B1 showed higher levels of PRL (plasma PRL/tumor size), as compared with the wild-type group." (PMID 32427851, 2020). "Due to the more recent demonstration of PRL production outside the pituitary gland, attempts have been made to modulate tumor production of PRL by using PRLR antagonists (PRLRA)." (PMID 32121009, 2020). "The longer latency of P300 in the pre-operative patients also suggests that both response activation and inhibition are significantly impaired at baseline by the prolactin-secreting tumor." (PMID 32848659, 2020). "The results showed that blockade of MAPK14 expression in the mice significantly reduced tumor formation in the pituitary gland, and thus PRL production and secretion in estradiol-induced and DRD2−/− prolactinoma." (PMID 32894113, 2020). "Practice guidelines for hyperprolactinemia suggest that a failure to achieve normal prolactin on maximally tolerated doses of DAs and a failure to achieve 50% reduction in tumor size should be regarded as DA-resistance." (PMID 31522358, 2020). "The goal of treatment is to relieve symptoms, normalize prolactin levels, induce tumor shrinkage and restore gonadal status, which can be achieved through medical therapy with dopamine agonists or surgical resection or a combination of both." (PMID 31665485, 2020). "The tumor cells of prolactinoma secrete excess prolactin, resulting in several symptoms such as sterility, hyperprolactinemia, amenorrhea, galactorrhea and pituitary space occupying lesion." (PMID 32894113, 2020). "Male patients typically have higher serum PRL levels and larger tumor volumes, exerting more aggressive and/or refractive behavior in comparison with female patients." (PMID 32188093, 2020). "Three patients, who underwent gamma knife surgery (GKS) owing to either resistance or intolerance to DAs or recurrence after the TSA, achieved a normal PRL level accompanied with marked tumor reduction and symptom remission." (PMID 32849307, 2020). "After 2 years however, the patient was found to have evidence of intraabdominal recurrent tumor and was then proven again to have elevated prolactin." (PMID 32857272, 2020). "Some case reports have shown that pasireotide LAR is able to normalize PRL levels and control symptoms after one month of treatment, inducing necrosis of the tumor cells and/or cystic degeneration." (PMID 32121432, 2020). "Cabergoline is the most effective DA available; it normalizes PRL levels, reduces tumor size, and restores gonadal function in 95% and 80% of patients with microprolactinomas and macroprolactinomas, respectively." (PMID 32121432, 2020). "Primary goals of treatment are reduction in tumor size, achievement of normal prolactin and restoration of gonadal function." (PMID 31522358, 2020). "For example, compared with studies reporting outcomes of patients treated with dopamine agonists, patients treated by transsphenoidal surgery had a lower median prolactin level and a smaller tumor diameter on study level." (PMID 31665485, 2020). "Dopamine reduces the secretion of prolactin and tumour volume by its suppressive effect on lactotrophic cells in the pituitary and by lowering the angiogenesesis in the surrounding tissue." (PMID 32429916, 2020). "It should be further underlined that previous studies have used different cut-offs, such as 50% decrease in prolactin levels or 30% reduction in craniocaudal diameter of the tumor." (PMID 31522358, 2020).
tumor (continued). "In summary, the present study elucidates the role of MAPK14 in promoting tumor growth, and the production and secretion of PRL through in vitro and in vivo experiments." (PMID 32894113, 2020). "One of the options is to switch to another DA since there is clear evidence that the switch to cabergoline can overcome resistance to bromocriptine, with a normalization of PRL and tumour mass reduction in 80 and 70% of the cases respectively." (PMID 32429916, 2020). "From a clinical perspective, these tumors are frequently resistant to dopamine agonists, both in terms of the reduction in prolactin levels and in tumor size." (PMID 31766255, 2019). "The major objectives of treatment for prolactinomas are to reduce the tumour mass, to relieve the neurological symptoms and to control the excess PRL secretion." (PMID 31000722, 2019). "There are a few therapeutic alternatives for DA-resistant prolactinomas, E. Sosa-Eroza reported that addition of octreotide to ongoing cabergoline treatment resulted in significant reductions in PRL levels and tumor volume in 2 out of 5 patients." (PMID 31191457, 2019). "Clinical studies have shown that BRC can effectively control serum prolactin levels in 80–90% of microadenomas and 70% of large adenomas and can effectively restore gonadal function in patients and reduce tumour volume." (PMID 31000722, 2019). "In order to address the long-term effects of STAT5 signaling deletion on PRL-induced tumor progression, we analyzed Pb-PRLSTAT5f/f and Pb-PRLΔSTAT5 mice at 12 and 18 months of age." (PMID 31269779, 2019). "On follow-up, there was cessation of cerebrospinal fluid leak, marked reduction of serum prolactin level, and imaging evidence of tumor shrinkage." (PMID 30766735, 2019). "BRC was reported to inhibit PRL secretion to shrink the tumour volume and induce apoptosis in GH3 cells." (PMID 31000722, 2019). "The frequent lactational activity of rabbit mammary gland tissue with and without proliferative lesions suggests a possible influence of prolactin on the development of mammary gland tumors and tumor-like lesions." (PMID 31581718, 2019). "This work confirmed STAT5 signaling as a major driver of autocrine PRL-mediated prostate tumorigenesis as genetically-induced STAT5 down-regulation delayed the onset of various PRL-induced tumor hallmarks." (PMID 31269779, 2019). "To determine if YAP/TAZ become elevated in aggressive/invasive tumours, we analysed their expression in one PRL-secreting carcinoma." (PMID 30139767, 2019). "These medications act by inhibiting PRL release and reducing tumor size, though side effects can reduce patient compliance." (PMID 31818039, 2019). "Unlike typical lactotroph tumors, where the degree of hyperprolactinemia is proportional to tumor size, in patients with acidophil stem cell tumors the blood prolactin levels are disproportionally low for the size of the tumor on imaging." (PMID 31766255, 2019). "These tumors express Pit1 in all tumor cells, but only the cells that express prolactin also express ERα." (PMID 31766255, 2019). "They induce apoptosis, autophagic cell death and paraptosis of lactotrophs through different molecular pathways mediated by D2R, leading to reduced prolactin secretion and tumour shrinkage." (PMID 31847209, 2019). "The closeness of this hormone with growth hormone and its functioning through tumour promoting Jak-STAT pathway strengthens the claim that prolactin has tumorigenic properties." (PMID 31795960, 2019). "This complex family of neoplasms can express multiple hormones, including GH, prolactin, β-thyroid stimulating hormone and/or α-subunit of glycoprotein hormones." (PMID 31766255, 2019). "Discrepancies between the response to the dopamine agonist in relation to normalization of prolactin levels and reduction of tumor mass have been described." (PMID 31202268, 2019).